PCSK9 (proprotein convertase subtilisin/kexin type 9)
Diseases named in the same sentence as PCSK9 in open-access papers (continued):
Sharing a sentence is not in itself a finding about the gene and the disease.
atherosclerosis (continued). "Proprotein convertase subtilisin/kexin type 9 (PCSK9) is considered to have multiple roles in the development of atherosclerosis, which is recently reported to participate in the thrombotic process." (PMID 34809656, 2021). "The relevance of PCSK9 in atherosclerosis progression is demonstrated by the benefits observed in patients that have followed PCSK9-targeted therapies." (PMID 33834043, 2021). "There is a strong background suggesting alternative roles for PCSK9 in the development of atherosclerosis." (PMID 33834043, 2021). "The GLP-1RA semaglutide reduced the development of atherosclerosis induced by viral PCSK9 expression in both Glp1rTie2+/+ and Glp1rTie2–/– mice." (PMID 34673572, 2021). "It has been reported that overexpression of PCSK9 enhances the development of atherosclerosis and knockout of PCSK9 reduces the levels of aortic cholesterol in apoE−/− mice." (PMID 33767172, 2021). "Although the present study proposes a new mechanism for the important role of PCSK9 in Hcy-induced lipid accumulation in macrophages and the acceleration of atherosclerosis, there are still some limitations in this study." (PMID 34660746, 2021). "Additionally, it could be shown that PCSK9 aggravates atherosclerosis in apolipoprotein-E deficient mice, which was associated with an increased expression of inflammatory cytokines such as TNF-α, IL-1β, IL-10, MCP-1, and IL-8 to directly facilitate the process of inflammation." (PMID 34884827, 2021). "By modulating the expression of low-density lipoprotein receptor (LDL-R), PCSK9 is a key regulator of cholesterol metabolism and a potential player in atherosclerosis and cardiovascular diseases." (PMID 34356905, 2021). "The gold standard treatment for atherosclerosis relies on lipid‐lowering, such as the administration of statin drugs and more recently, PCSK9 inhibitors." (PMID 33231376, 2021). "In other words, in this research, the binding affinity of the top selected molecules showed the best affinity with the PCSK9 target protein for atherosclerosis." (PMID 34351937, 2021). "This study and previous ones indicate that PCSK9 is involved in the pathophysiology of atherosclerosis and thrombosis." (PMID 34681838, 2021). "In another study that included 643 participants, high plasma PCSK9 levels correlated with enhanced atherosclerosis progression independently of LDL, as measured by carotid plaque formation and total plaque area." (PMID 33834043, 2021). "PCSK9 is expressed on various cells types that are involved in atherosclerosis: endothelial cells, VSMCs, and macrophages." (PMID 34199468, 2021). "Proprotein convertase subtilisin/kexin type 9 (PCSK9) is one of the key targets for atherosclerosis drug development as its binding with low-density lipoprotein receptor leads to atherosclerosis." (PMID 34351937, 2021). "Based on these results, PSCK9 was highlighted as the therapeutic target of atherosclerosis, and several studies have been conducted to test the potential for functional inhibition of PCSK9 using antibody mechanisms." (PMID 34071276, 2021). "Our study further supports a direct role of PCSK9 in vascular biology and SMC migration and proliferation—two pivotal features of atherosclerosis—and adds a new pharmacological aspect in the influence of PCSK9 on the pleiotropic effects of statins." (PMID 33923431, 2021). "A plethora of experimental and clinical studies have established the central role of PCSK9 in lipid metabolism while robust evidence supports the implication of PCSK9 in the inflammatory nature of atherosclerosis." (PMID 34336112, 2021). "Recently investigations suggest that liraglutide can suppress PCSK9 expression in diabetes-influenced hepatocytes, and PCSK9 plays an important role in atherosclerosis." (PMID 34666623, 2021).
atherosclerosis (continued). "PCSK9’s impacts on atherosclerosis progression has been proved by the benefits observed in patients who followed PCSK9-targeted therapies." (PMID 34070931, 2021). "Proprotein convertase subtilisin/kexin type 9 (PCSK9), an enzyme involved in low-density lipoprotein receptor degradation has been shown to not only promote early atherosclerosis but also being ubiquitously present in the body including neural tissue." (PMID 33916056, 2021). "This suggested that targeting either circulating or liver PCSK9 should markedly reduce LDL-C and associated atherosclerosis." (PMID 34606887, 2021). "It must, however, be noted that PCSK9 inhibitors are relatively new drugs, and therefore further research is needed to assess their long-term effects on atherosclerosis development and to find the most effective treatment strategies." (PMID 34071103, 2021). "The role of PCSK9 during atherosclerosis progression in the adaptive immune system has been studied." (PMID 33834043, 2021). "Beyond the key role of PCSK9 on lipid disorders and management, emerging evidence points out its determining implication in the inflammatory arm of atherosclerosis." (PMID 34336112, 2021). "Different studies show that PCSK9 is involved in other mechanisms that take place at different stages during atherosclerosis development." (PMID 33834043, 2021). "Mediated by mitochondrial ROS generation, PCSK9 and mitochondrial DNA damage influence each other in a positive feedback loop to facilitate cell injury and thereby advance atherosclerosis." (PMID 34356856, 2021). "Overexpressed PCSK9 accumulates in the arterial wall and directly affects atherosclerosis lesion size and composition, independently of plasma lipid and lipoprotein concentrations." (PMID 34199468, 2021). "In the results, the top 10 compounds with binding energies from -9.8 to -8.2 kcal/mol, are comparable to the reference compounds and hence are favorable and valid potential drug candidates for targeting PCSK9 in atherosclerosis." (PMID 34351937, 2021). "Recent observations suggest that PCSK9 is involved in inflammation processes with implications in atherosclerosis and its major consequence—myocardial ischemia." (PMID 35024053, 2021). "Albeit the steps involved in atherogenesis have already been clearly outlined by various studies, the exact role of PCSK9 in atherosclerosis has only recently been (partly) unravelled." (PMID 34356856, 2021). "Mice with a PCSK9 deficiency appear to have a similar phenotype to PCSK9-deficient humans with low levels of LDL-C and protection from atherosclerosis." (PMID 34070931, 2021). "More recently, studies have been discussing the potential role of PCSK9 and the PCSK9 inhibitors in atherosclerosis." (PMID 34869702, 2021). "Studies investigating the role of PCSK9 in atherosclerosis beyond LDL-C regulation completely lack in the CKD high-risk population." (PMID 34336112, 2021). "Third, we used ApoE−/− mice fed a methionine diet to clarify the role of PCSK9 in atherosclerosis accelerated by Hcy." (PMID 34660746, 2021). "This indicates that PCSK9 is a chemotactic and proinflammatory factor that promotes atherosclerosis." (PMID 34681838, 2021). "Recent findings indicate the participation of PCSK9 in other processes beyond lipid homeostasis such as cell cycle, apoptosis, and inflammation with a potential effect on atherosclerosis." (PMID 33440821, 2021).
atherosclerosis (continued). "As commonly recognized, PCSK9, a novel regulator of cholesterol metabolism, takes part in atherosclerosis, leading to the occurrence of CAD." (PMID 34809656, 2021). "Briefly, PCSK9 is expressed in endothelial cells, and at a low level, in macrophages, implying a potential role of PCSK9 in atherosclerosis plaque development." (PMID 35071356, 2021). "A clear effect of anti-atherosclerosis on lipoprotein(a)is exerted by protein convertase subtilisin/kexin type 9 (PCSK9) antagonists." (PMID 34869651, 2021). "These additional pathways further illustrate the regulatory role of PCSK9 in atherosclerosis and offer an in-depth interpretation of how the PCSK9 inhibitor exerts effects on the treatment of atherosclerosis." (PMID 32169071, 2020). "Among the population with loss-of-function (LOF) variation of PCSK9, there was a remarkable decline of serum LDL cholesterol (LDL-C) level as well as the prevalence of atherosclerosis." (PMID 33123601, 2020). "Increased expression and activity of PCSK9 in those cells led to inflammation and further to atherosclerosis." (PMID 32456228, 2020). "In order to induce atherosclerosis development we used the AAV-PCSK9 system to overexpress PCSK9 stable in the liver." (PMID 32949971, 2020). "Apart from this classical pathway, recent studies have described other roles played by PCSK9 in atherosclerosis." (PMID 32169071, 2020). "Based on these findings, it appears that PCSK9 functions as an inflammatory mediator by exacerbating vascular inflammation via the TLR4/NF-κB signaling pathway in the pathogenesis of atherosclerosis." (PMID 32169071, 2020). "Numerous studies have attempted to clarify the pro-inflammatory roles of PCSK9 in a variety of disorders including atherosclerosis, sepsis, psoriasis, steatosis, and myocardial ischemia." (PMID 33488522, 2020). "Accordingly, the mechanisms of PCSK9 in atherosclerosis can be grouped into intracellular and extracellular mechanisms." (PMID 32169071, 2020). "Based on this finding, it was proposed that mtROS generation followed the same pattern as PCSK9 expression, and their interaction was significant in the pathogenesis of atherosclerosis." (PMID 32169071, 2020). "We also found widespread losses of PCSK9 and CETP genes, where loss-of-function mutations in humans protect from atherosclerosis." (PMID 33575564, 2020). "PCSK9 is a newly identified protein that shows potential in the treatment for dyslipidemia and atherosclerosis." (PMID 32325897, 2020). "PCSK9 reduces the hepatic uptake of atherosclerosis-promoting low-density lipoproteins (LDL) by targeting the LDL receptor for degradation." (PMID 33575564, 2020). "TLR4/NF-κB signaling pathway is involved in the regulation of PCSK9 on atherosclerosis inflammation." (PMID 31957804, 2020). "Multiple studies have proven the anti-oxidative effects of PCSK9 suppression in several disorders including atherosclerosis and myocardial infarction." (PMID 33488522, 2020). "There has been a shift toward the use of a PCSK9-overexpressing AAV to drive atherosclerosis in genetic mouse models; however, this new method makes it unfortunately difficult to compare previous studies." (PMID 32978273, 2020). "In this review the role of PCSK9 in lipid homeostasis was elucidated, the effect of PCSK9 on atherosclerosis was highlighted, and contemporary therapeutic techniques that focused on PCSK9 were summarized." (PMID 33062601, 2020). "PCSK9 can accelerate atherosclerosis by reducing ABCA1 expression in the macrophages, thereby inhibiting RCT." (PMID 32169071, 2020). "Atherosclerosis was studied in vivo by infecting Rac1fl/fl and Rac1fl/fl/LC mice with AdPCSK9 (adenoviral vector overexpressing proprotein convertase subtilisin/kexin type 9)." (PMID 32941503, 2020).
atherosclerosis (continued). "Their data demonstrated that patients with high PCSK9 levels also had high fibrinogen levels; thus, circulating PCSK9 and fibrinogen levels were positively correlated with atherosclerosis." (PMID 32169071, 2020). "Elucidating in detail the mechanisms by which PCSK9 affects atherosclerosis is important for guiding clinical medication of PCSK9 inhibitors." (PMID 32169071, 2020). "Current therapeutic strategies for atherosclerosis work by lowering cholesterol levels (statins, PCSK9 antibodies), reducing platelet functions, and controlling arterial tone." (PMID 31824304, 2019). "The use of statins and more recently PCSK9 inhibitors has led to atherosclerosis regression and reductions in vascular events." (PMID 31784656, 2019). "Beyond the trials testing the LDL-C lowering efficacy, safety, and impact on atherosclerosis, each of the individual PCSK9 inhibitors has been evaluated in the context of large, dedicated cardiovascular outcomes trials." (PMID 30895178, 2019). "In ACC 2017, a large-scale clinical study called Further cardiovascular OUtcomes Research with PCSK9 Inhibition in subjects with Elevated Risk (FOURIER) trial was published, which focused on the effect of PCSK9 inhibitor to atherosclerosis." (PMID 29334984, 2018). "Existing therapeutic approaches for the prevention and treatment of atherosclerosis heavily involve statins or PCSK9 antibodies to reduce hypercholesterolemia." (PMID 30115989, 2018). "It is well known that dramatic lipid-lowering therapies, such as statins or PCSK9 inhibitors, improve atherosclerosis in humans and mice, and that atherosclerosis has a strong inflammatory component." (PMID 30282904, 2018). "PCSK9 inhibitors after being established as a valid option, now its effects on inflammation, endothelial function, atherosclerosis, diabetes, and obesity are now actively investigated." (PMID 29770231, 2018). "In general, the levels of serum PCSK9 exceeded 10,000 ng/mL which is sufficiently high to induce atherosclerosis upon prolonged WTD feeding." (PMID 30619297, 2018). "This position statement of the Atherosclerosis Department of the Rio Grande do SulSociety of Cardiology identifies patients who can derive the greatest secondaryclinical benefit from PCSK9 inhibition." (PMID 30110052, 2018). "Nevertheless, in light of the fact that PCSK9 is an important target for the prevention and treatment of atherosclerosis and lipid homeostasis, the clinical effect of additional PCSK9 inhibition during cilostazol treatment warrants further investigation." (PMID 29296222, 2017). "PCSK9 inhibitors apart from obvious ability to reduce LDL can inhibit the progression of atherosclerosis by modifying the profile of pro-inflammatory cytokines, adhesion factors, and regulatory proteins." (PMID 29209441, 2017). "Taken together, PCSK9 protein is an important target for the prevention and treatment of atherosclerosis." (PMID 29296222, 2017).
atherosclerosis (continued). "New approaches to lowering LDL by blocking the effect of PCSK9, and a strategy of treating atherosclerosis directly instead of focusing on intermediate targets, show promise of reducing the residual risk that remains after current therapy." (PMID 27540477, 2016). "Altogether, our results bring forward a new pleiotropic role for PCSK9 in lymphatic function and unveil new potential therapeutic targets for the prevention and treatment of atherosclerosis." (PMID 27279328, 2016). "On the contrary, development of atherosclerosis is slowed down by inactivation of the PCSK9 gene in mice." (PMID 25600226, 2015). "This is the first study to show that a monoclonal antibody to PCSK9 reduces atherosclerosis development." (PMID 25139399, 2014). "Second, due to the “knock-out” nature of the gene disruption, a more severe, and thus more rapidly developing, atherosclerosis is possible in the homozygotes compared to the Rapacz or PCSK9-D374Y transgenic pigs." (PMID 24691380, 2014). "The mechanism whereby PCSK9 contributes to the risk of MI has been attributed largely to its effect on degrading the LDL-R, thereby elevating LDL-C and promoting atherosclerosis." (PMID 25180781, 2014). "The D374Y-PSSK9 gain-of-function mutation in the proprotein convertase subtilisin/kexin type 9 (PCSK9) gene causes severe autosomal dominant hypercholesterolemia and early development of atherosclerosis in humans." (PMID 23844374, 2013). "PCSK9 is a crucial regulator of atherosclerosis by controlling LDL-C levels." (PMID 40354375, 2025). "The authors hypothesized that ROS may regulate PCSK9 expression and the development of atherosclerosis in arterial channels with low shear stress." (PMID 39982361, 2025). "PCSK9 disrupts the normal LDL-R recycling process, reducing the liver’s ability to clear serum LDL-C and leading to its accumulation, thereby increasing CVD risk and accelerating atherosclerosis development." (PMID 40362720, 2025). "Specifically, PCSK9 has been shown to induce senescence and apoptosis in vascular smooth muscle cells, which are critical processes in the development of degenerative vascular diseases such as atherosclerosis and aneurysms." (PMID 40764605, 2025). "Similarly, LincRNA-p21 shows promise as a therapeutic target for preventing atherosclerosis development through its regulation of the miR-221/SIRT1/PCSK9 axis." (PMID 40764605, 2025). "To test whether KD of Casz1 and/or Zfp961 could reduce atherosclerosis, we used a mouse atherosclerosis model, in which all adult mice were transduced with mutant mouse gain-of-function Pcsk9 (mPcsk9)." (PMID 39782688, 2025). "Altogether, this suggests that PCSK9 inhibitors may have additional benefits for atherosclerosis treatment beyond reducing LDL cholesterol." (PMID 39445733, 2025). "PCSK9 activates the atherosclerosis process through pro-inflammation signaling." (PMID 40076547, 2025). "To verify that the observed changes between weight cycling and non–weight cycling bone marrows are not due to age differences of donors, we repeated the bone marrow transplant study with age-matched PR and WR donors and induced atherosclerosis in naive CD45.1 recipients with Pcsk9-AAV.8 (as above)." (PMID 40627456, 2025). "PCSK9 plays an important role in the pathogenesis of atherosclerosis." (PMID 40823653, 2025). "A Chinese group recently reported that the combination of polycosanol and atorvastatin in atherosclerosis patients could attenuate the statin-induced elevation of serum Proprotein Convertase Subtilisin/Kexin type 9 (PCSK9) levels." (PMID 40509530, 2025).